SLC6A3 (solute carrier family 6 member 3)
Diseases named in the same sentence as SLC6A3 in open-access papers (continued):
Sharing a sentence is not in itself a finding about the gene and the disease.
Hypertension (8 papers, 2018 to 2025). The presence of chronic increased pressure in the systemic arterial system. "Among them, three DEGs (Cyp11b2, Ptgds, and Slc6a3) were found to be associated with both behavior and hypertension." (PMID 36140769, 2022). "The analysis revealed three genes (Cyp11b2, Ptgds, and Slc6a3) related to both hypertension and the behavior/neurological phenotype." (PMID 36140769, 2022).
migraine (8 papers, 2009 to 2024). "Risk variants and haplotypes in dopamine metabolism genes, DBH, DDC, MAOA, and SLC6A3, are reported to influence migraine risk, as are variants in the oestrogen receptor gene, ESR1." (PMID 22030984, 2011). "The genes for dopamine beta-hydroxylase and the dopamine transporter SLC6A3 may be involved in the pathogenesis of migraines." (PMID 37373239, 2023). "Consequently, the target SLC6A3 (dopamine transporter) fully participates in the pathogenesis of migraines." (PMID 36079577, 2022).
post-traumatic stress disorder (8 papers, 2006 to 2025). An anxiety disorder precipitated by an experience of intense fear or horror while exposed to a traumatic (especially life-threatening) event. "Recent work suggests that the 9-repeat (9R) allele located in the 3′UTR VNTR of the SLC6A3 gene increases risk of posttraumatic stress disorder (PTSD)." (PMID 22745713, 2012).
renal cell carcinoma (8 papers, 2016 to 2025). "SLC6A3 functions as a dopamine transporter, as can be found overexpressed in cancers, including renal cell carcinoma and gastric cancer." (PMID 39495297, 2024). "In accordance with this, SLC6A3 was recently identified as a biomarker for patients suffering from renal cell carcinoma." (PMID 32102440, 2020). "A high expression of DAT/SLC6A3 mRNA was found in renal cell carcinoma, lung adenocarcinoma, prostate cancer, lung SCC, pancreatic cancer, ovarian cancer, stomach cancer, esophagus cancer, sarcoma, and head and neck cancer." (PMID 32102440, 2020). "The results of our analysis of the renal cell carcinoma TCGA dataset were consistent with latest reports, that indicated SLC6A3 as a experimentally confirmed biomarker for RCC." (PMID 33287006, 2020). "Some reports have shown that the expression level of SLC6A3 is significantly higher in gastric carcinoma, hepatocellular carcinoma, and renal cell carcinoma than in control tissues, and that it may be related to increased metastasis and proliferation." (PMID 37628576, 2023). "In addition, SLC6A3 was also found overexpressed and functioning in kidney cancer and was suggested as a biomarker for patients with renal cell carcinoma." (PMID 35401884, 2022). "The dopamine transporter SLC6A3 was identified as a biomarker for renal cell carcinoma." (PMID 32388640, 2020).
substance abuse (7 papers, 2013 to 2024). The use of a drug for a reason other than which it was intended or in a manner or in quantities other than directed. "Significant differences between addicts and controls in relation to schooling, marital status, social security family history of substance abuse (p <0.001), Int8-VNTR SLC6A3 gene (p= 0.015) and SNP 3435C>T ABCB1 gene (p= 0.001) were found." (PMID 24892317, 2013).
alcohol use disorder (6 papers, 2015 to 2023). "Both the dopamine transporter gene SLC6A3 (ρ = 0.967), a candidate risk gene for dopamine or other toxins in the dopamine neurons and aldehyde dehydrogenase-1 (ALDH1A1, ρ = 0.949), whose polymorphisms are implicated in alcohol use disorders, map to module M12 (ρ = 0.949)." (PMID 37079537, 2023).
delirium (6 papers, 2014 to 2024). A disorder characterized by confusion; inattentiveness; disorientation; illusions; hallucinations; agitation; and in some instances autonomic nervous system overactivity. "The SLC6A3 gene is coding for the dopamine transporter, hence variation of this gene can lead to a lower concentration of cerebral basal dopamine, diminishing the risk of delirium." (PMID 26106326, 2015). "The SLC6A3 gene could affect availability or function of dopamine transporters; lower cerebral basal dopamine concentration could diminish risk for delirium." (PMID 24795632, 2014). "Seven single nucleotide polymorphisms (SNPs) in the SLC6A3 (solute carrier family 6, member 3) gene and three genetic polymorphisms in the DRD2 gene are associated with delirium." (PMID 26106326, 2015). "A further meta-analysis concluded that the homozygous AA genotype of rs393795 in the SLC6A3 gene was more frequent in patients without delirium, and the homozygous GG genotype of rs6276 in the DRD2 gene was more frequent in patients without delirium after adjustment for cognitive impairment." (PMID 24795632, 2014).
mood disorder (6 papers, 2013 to 2025). A cognitive disorder a disturbance in which the person's mood is hypothesized to be the main underlying feature. "Although the association between SLC6A3 40 bp VNTR-polymorphism and mood disorders, as well as personality traits, was described, there was no information about an effect of this locus on suicidal tendencies." (PMID 34199792, 2021).
Atrophy (5 papers, 2019 to 2026). Any weakening or degeneration, especially through lack of use. "Individuals with spastic paraplegiamay present with atrophy of the spinal cord and defects in the upper limbs.These results indicate that SLC6A3, CCT5 and TPPP showimportant connection." (PMID 30985858, 2019).
breast carcinoma (5 papers, 2014 to 2025). "Another DEG, SLC6A3, which has already been implicated in lung and breast cancer, was here found to be involved in KIRC for the first time." (PMID 28029655, 2017). "Another differentially expressed gene, SLC6A3, which is implicated in lung and breast cancer, has not yet been well known in KIRC." (PMID 25559354, 2014).
dopamine transporter deficiency syndrome (5 papers, 2014 to 2025). "Most importantly, a causal relationship between DAT dysfunction and human disease was established with the description of DAT deficiency syndrome (DTDS), in which inactivating mutations in SLC6A3 give rise to a recessively inherited form of infantile parkinsonism dystonia." (PMID 34375312, 2021).
gastric cancer (5 papers, 2020 to 2024). A primary or metastatic malignant neoplasm involving the stomach. "It has been confirmed that the expression level of SLC6A3 is significantly higher in gastric cancer patients than that in control subjects." (PMID 38494840, 2024). "SLC6A3 has previously been reported as a potential circulating biomarker for gastric cancer detection and progression monitoring." (PMID 35401884, 2022).
clear cell renal cell carcinoma (4 papers, 2019 to 2025). "SLC6A3 is also found highly expressed in clear cell renal cell carcinoma, which indicates as powerful therapeutic biomarkers for human renal cancer diagnosis and treatment." (PMID 31641374, 2019).
Onset (4 papers, 2022 to 2025). The age group in which disease manifestations appear.
dyslexia (3 papers, 2012 to 2024). A learning disorder characterized by an impairment in processing written words. "In our investigation, we only identified one SNP marker in SLC6A3 showing significant association with dyslexia after adjustment for age and sex, which located in the 3’- untranslated region (3’-UTR)." (PMID 25178928, 2014). "For instance, the dopamine transporter gene (SLC6A3/DAT) has been implicated in the pathogenesis of several speech and language disorders, including dyslexia and stuttering." (PMID 25178928, 2014). "In SLC6A3, we genotyped 12 Tag SNPs and found nominal association of one SNP with dyslexia before adjustment." (PMID 25178928, 2014). "The inconsistent association of SLC6A3 with dyslexia between our study and previous western studies might be explained by linguistic and genetic differences among various populations." (PMID 25178928, 2014). "We proposed that stuttering candidate genes, DRD2 and SLC6A3, might be associated with dyslexia." (PMID 25178928, 2014). "The association between the 10-repeat SLC6A3 allele and neurodevelopmental disorders (i.e., ADHD and dyslexia) has been reported." (PMID 25178928, 2014). "Here, we aimed to examine the association between dyslexia and dopaminergic genes (dopamine receptor DRD2 and dopamine transporter SLC6A3)." (PMID 25178928, 2014). "Based on existing findings, dopaminergic genes DRD2 and SLC6A3 are believed to be candidate genes for dyslexia." (PMID 25178928, 2014).
heroin dependence (3 papers, 2013 to 2023). Physical and psychological dependence on the drug heroin. "This study aimed to identify the association between genetic polymorphisms of DA synthesis and metabolism genes, including tyrosine hydroxylase (TH), DOPA decarboxylase (DDC), solute carrier family 6 member 3 (SLC6A3) and DA beta-hydroxylase (DBH), with six important phenotypes of heroin dependence." (PMID 32736537, 2020).
Visual hallucination (3 papers, 2019 to 2025). Visual perception in the absence of a visual stimulus. "In addition, a recent study in Slovenia demonstrated that the haplotype of the SLC6A3 gene was associated with the development of levodopa-induced visual hallucinations in PD patients." (PMID 35741861, 2022). "Additionally, haplotypes of COMT and SLC6A3 were associated with the occurrence of visual hallucinations (AT vs. GC: OR = 0.34; 95% CI = 0.16–0.72; p = 0.005) and orthostatic hypotension (ATG vs. ACG: OR = 2.48; 95% CI: 1.01–6.07; p = 0.047), respectively." (PMID 30745869, 2019).
colorectal adenocarcinoma (2 papers, 2020 to 2025). The most common type of colorectal carcinoma. "SLC6A3 is a well-known dopamine transporter, and studies indicate that SLC6A3 expression changes in kidney and colorectal adenocarcinomas may be a marker of cancer malignancy and that SLC6A3 gene changes affect cancer prognosis." (PMID 40362545, 2025). "Next, we therefore searched to determine whether the expression of STAT3 and DAT/SLC6A3 were correlated with the expression of other genes related to the STAT and NF-κB signals in colorectal adenocarcinoma patient-derived samples (594 cases)." (PMID 32102440, 2020).
COVID-19 (2 papers, 2022 to 2025). A disease caused by infection with severe acute respiratory syndrome coronavirus 2. "Using network pharmacology, we identified 7 core targets of curcumol against COVID-19 and COAD, including GABRD, GABRP, BCHE, CYP3A4, PGR, HSD17B2, and SLC6A3." (PMID 35967794, 2022).
periodontitis (2 papers, 2022 to 2026). An acute or chronic inflammatory process that affects the tissues that surround and support the teeth. "The AUC for CDSN, TH, DDC, and SLC6A3 in periodontitis patients and normal controls were 0.889 (95% confidence interval [CI], 0.581–1.000, p < 0.05), 0.444 (95% CI, 0.000–1.000; p < 0.05), 0.778 (95% CI, 0.291–1.000; p < 0.05), and 0.778 (95% CI, 0.291–1.000; p < 0.05), respectively." (PMID 36437997, 2022).
ameloblastoma (1 paper, 2023). The most common odontogenic tumor, arising from the epithelial component of the embryonic tooth and usually affecting the molar-ramus region of the mandible or maxilla. "We identified LRP5, SLC6A3, and SOX10 as potentially important genes related to the cell proliferation and invasion of ameloblastomas through a large-scale gene expression analysis using a microarray approach, validating the expression results through immunohistochemical assays." (PMID 37628576, 2023). "In ameloblastoma, the overexpression of SOX10, LRP5, and SLC6A3 may possibly be related to increased cell proliferation, local invasion, and high recurrence rates; as such therapeutic alternatives such as parthenolide and vorinostat may be employed as inhibitors of these genes." (PMID 37628576, 2023).
Becker muscular dystrophies (1 paper, 2016). "While KCNJ10 and SLC6A3 codify for ion channels and thus their contribution to epileptogenesis is not unexpected, DMD codes for dystrophin, which has been traditionally associated with X-linked Duchenne and Becker muscular dystrophies." (PMID 27984588, 2016).
Developmental delay (1 paper, 2022).
endometrial cancer (1 paper, 2024). Primary or metastatic malignant neoplasm involving the endometrium (mucous membrane that lines the endometrial cavity). "It is unclear how the loss of function of LPCAT1, TERT or SLC6A3 might contribute to endometrial cancer risk." (PMID 39495297, 2024).
glioblastoma (1 paper, 2020). The most malignant astrocytic tumor (WHO grade IV). "This statement can also be supported by the involvement of SLC6A3 in response to hypoxia, in glioblastomas, as one of the target genes of HIF-1." (PMID 32599859, 2020). "Concerning its role in human malignancies, SLC6A3 is also a target gene of Hypoxia Inducible Factor 1 (HIF-1), and thus its expression has recently been studied in glioblastomas in response to oxygen decline." (PMID 32599859, 2020).
GM1 gangliosidosis (1 paper, 2025). A rare lysosomal storage disorder characterized biochemically by deficient beta-galactosidase activity and clinically by a wide range of variable neurovisceral, ophthalmological and dysmorphic features. "While GM1 gangliosidosis and PLAN are relatively more common diseases, the total number of reported cases in the literature for SLC6A3, SLC30A10, and SLC39A14 is approximately 50 for each condition." (PMID 40362326, 2025).
Hip dysplasia (1 paper, 2025). The presence of developmental dysplasia of the hip. "For example, solute carrier family 6 member 3 (slc6a3) has been implicated in canine hip dysplasia, with associated SNPs found in genes that contain slc6a3." (PMID 39857294, 2025).
hippocampal atrophy (1 paper, 2024). "Interestingly, DAT1 (dopamine transporter 1, also known as SLC6A3) and BDNF polymorphisms interact to predict Abeta and tau pathology, as well as hippocampal atrophy." (PMID 39194496, 2024).
ischemic stroke (1 paper, 2024). A stroke disorder caused by obstruction of blood flow to the brain, due to thrombotic (local blood clot formation) or embolic (due to a blood clot or other material traveling from another site) event. "The effect of DAT on ischemic stroke was investigated by using Slc6a3 homozygous mutation and WT mice (n = 10, 20 g ±)." (PMID 39467829, 2024).
lymph node metastasis (1 paper, 2016). "SLC6A3 protein expression was increased in patients with distant metastasis (p = 0.002), but not correlated to AJCC stage, pT-stage, lymph node metastasis nor grading (all p > 0.1)." (PMID 26831905, 2016).
medulloblastoma (1 paper, 2014). A malignant, invasive embryonal neoplasm arising from the cerebellum. "We confirmed SNCAIP as exclusively expressed in Group 4 medulloblastoma, and we also identified SLC6A3 as a significantly over-expressed and highly connected pathway member." (PMID 25412507, 2014).
melanoma (1 paper, 2022). A malignant, usually aggressive tumor composed of atypical, neoplastic melanocytes. "No studies have reported on the relationship between the SLC6A3 gene mutation and melanoma or QOL, and further research in this area is needed." (PMID 36405903, 2022).
oculogyric crisis (1 paper, 2025). A focal dystonia that is characterized by a prolonged involuntary upward deviation of the eyes. "While certain features like seizures or oculogyric crisis may be found in GLB1 and PTS, or SLC6A3 and SPR, respectively, levodopa response is more inconsistent in GLB1, SLC6A3, SLC30A10, and SLC39A14, and should guide the diagnosis." (PMID 40362326, 2025).
triple-negative breast carcinoma (1 paper, 2019). An invasive breast carcinoma which is negative for expression of estrogen receptor (ER), progesterone receptor (PR), and human epidermal growth factor receptor 2 (HER2). "Recently, SLC6A3 is proposed as poor prognostic biomarker in human triple negative breast cancer tissues." (PMID 31641374, 2019).
psychiatric disorder (44 papers, 2010 to 2025). A disorder characterized by behavioral and/or psychological abnormalities, often accompanied by physical symptoms. "Central among these were cytokine signaling (e.g., IL‐1β, IL‐8) and dopaminergic transmission (DRD2, SLC6A3), underscoring the intricate crosstalk between the immune system and brain function in the pathophysiology of severe mental illness." (PMID 40922454, 2025). "SLC6A3 has not been identified as a risk gene in GWAS studies of psychiatric disease or neurological disorders." (PMID 34375312, 2021). "Dopamine transporter DAT-1 (SLC6A3) and DRD2 gene for the dopamine-2 receptor are dopaminergic system genes that regulate dopamine reuptake and signaling, and may be part of the pathogenesis of psychiatric disorders including antisocial behaviors and traits." (PMID 28582390, 2017).
movement disorder (31 papers, 2014 to 2026). Neurological conditions resulting in abnormal voluntary or involuntary movement, which may impact the speed, fluency, quality and ease of movement. "We propose that mutations in SLC6A3 not only cause disease in infancy, but can also result in a phenotypic spectrum of severe progressive movement disorders with onset in childhood/adolescence and also in adulthood that has not been previously reported." (PMID 24613933, 2014).
neurological disorders (18 papers, 2009 to 2025). "Of these genes, SLC6A3 has gained recognition as a risk factor due to its association with various familial mutations related to neuropsychiatric and neurological disorders." (PMID 38159255, 2023). "In this risk synthesis, we have concluded that SLC6A3 represents an increasingly recognized risk with a growing number of familial mutants associated with neuropsychiatric and neurological disorders." (PMID 34650206, 2022). "The dopamine transporter (DAT) is a principal regulator of dopaminergic neurotransmission and its gene (the SLC6A3) is a strong biological candidate gene for various behavioral- and neurological disorders." (PMID 21826203, 2011).